TNF (tumor necrosis factor)
Diseases named in the same sentence as TNF in open-access papers (continued):
Sharing a sentence is not in itself a finding about the gene and the disease.
onychodystrophy (1 paper, 2025). "Among the patients treated with anti-tumor necrosis factor agents, onychodystrophy has been reported as the symptom showing the least improvement." (PMID 41235080, 2025).
opisthorchiasis (1 paper, 2018). Infection with flukes of the genus Opisthorchis. "This study aimed to investigate risk factors for ICC with a focus on opisthorchiasis and polymorphisms of proinflammatory cytokines (IL-1β and TNF-α)." (PMID 30139338, 2018).
orbital pseudotumor (1 paper, 2008). "In addition to radiation, cytotoxic agents, immunosuppressant, IV immunoglobulin, biological therapy, TNF-alpha inhibitor monoclonal antibody and Mycophenolate Moftil have been found to be useful in the management of refractory orbital pseudotumor." (PMID 20379424, 2008).
organic acidemia (1 paper, 2013). "Considering that IL-1β can also inhibit glutamate uptake in astrocytes and increase its glial release possibly via TNF-α production, the increase of pro-inflammatory cytokines may result in elevated extracellular glutamate levels and toxicity in this model of organic acidemia." (PMID 24205200, 2013).
Orofacial dyskinesia (1 paper, 2023). "After multiple administrations to rats of haloperidol, risperidone and reserpine striatal TNF-α levels invariably increased, with only in the case of risperidone this exposure not being associated with orofacial dyskinesia." (PMID 37810262, 2023). "Moreover, TNF-α knockout mice exhibited an exacerbation of haloperidol-induced orofacial dyskinesia, which also persisted longer than in wild-type mice." (PMID 37810262, 2023).
osteophytes (1 paper, 2025). "COMP had an AUROC of 0.604 (0.543,0.664) for new cases of JSN, COMP, IL-1β and leptin had an AUROC 0.586 (0.524,0.646) for new osteophytes, and TNF-α, IL-1β and adiponectin had an AUROC 0.590 (0.520,0.659) for new sclerosis." (PMID 41194279, 2025).
osteosclerosis (1 paper, 2018). Abnormally high bone density. "Various cytokines containing tumor necrosis factor (TNF) made up a complex network, mediating development, and maintenance of osteosclerosis." (PMID 30622613, 2018).
ototoxicity (1 paper, 2025). damage to the ear, specifically the cochlea or auditory nerve as a result of some toxic stimulus, eg from a drug. "TNF-α precondition induced BMSCs-derived exosomes are proposed as a novel therapeutic agent to promote regeneration and immunomodulation of cisplatin-induced ototoxicity." (PMID 40027193, 2025).
Overgrowth (1 paper, 2010). Excessive postnatal growth which may comprise increased weight, increased length, and/or increased head circumference. "The findings of the present study suggest that CsA can modify the expression of TNF-α and RANTES in drug-induced human gingival overgrowth." (PMID 20871770, 2010).
paraneoplastic neurological syndromes (1 paper, 2019). "The purpose of our study was to examine serum markers of BBB breakdown and serum concentrations of proinflammatory (TNF-alpha, VEGF) and anti-inflammatory/immunosuppressive (IL-4) cytokines in patients with paraneoplastic neurological syndromes." (PMID 30374596, 2019).
parathyroid carcinoma (1 paper, 2024). "Tumors such as parathyroid carcinoma, as well as other malignancies, can produce a range of endogenous pyrogens (e.g., interleukins, tumor necrosis factor-alpha) that influence the hypothalamic regulation of body temperature." (PMID 39822449, 2024).
pasteurellosis (1 paper, 2021). Infections with bacteria of the genus pasteurella. "Therefore, in this study we have investigated the impact of vitamin C on the production of pro-inflammatory cytokines (IL-1β, IL-6, IL-12p40, IFN-γ, and TNF-α) in lambs naturally infected by pneumonic pasteurellosis." (PMID 34944151, 2021). "Moreover, elevated expression of IL1-β and TNF-α were detected in the respiratory airways and lung lesions of calves with pneumonic pasteurellosis." (PMID 34944151, 2021). "Wilks’ lambda test for drug × time interaction, p < 0.0001) of vitamin C, a major water-soluble vitamin in normalization the pro-inflammatory cytokines (IL-1β, Il-6, IFN-γ, and TNF-α) when used in combination with tulathromycin in lambs with pneumonic pasteurellosis." (PMID 34944151, 2021).
pediatric acute respiratory distress syndrome (1 paper, 2022). "Annotation: PARDS: pediatric acute respiratory distress syndrome; TNF-α, tumor necrosis factor -alpha; IL-6, interleukin-6; IL-1β; IL-17: interleukin-17." (PMID 35506305, 2022).
pediatric cancer (1 paper, 2025). "In pediatric cancer, TNF-α has been shown to promote de-differentiation of OS, Furthermore, the immature state of pediatric T-cells has been shown to contribute to reduced expression of CD40, a tumor necrosis factor receptor family member." (PMID 39796780, 2025).
Pediatric Multisystem Inflammatory Syndrome (1 paper, 2023). "Early consideration of biologics such as anti-TNF-α has been suggested for the treatment of a newly reported clinical entity called Pediatric inflammatory multisystem syndrome-temporally associated with SARS-CoV-2 (PIMS-TS) or Pediatric Multisystem Inflammatory Syndrome (MIS-C)." (PMID 36698148, 2023).
penile cancer (1 paper, 2020). A primary or metastatic malignant neoplasm that affects the penis. "IPA identified potential upstream regulators that explain the transcriptional changes of human penile cancer, which included activated targets by pro-inflammatory factors such as TNF, CSF2, IFNγ, IL1B, and inhibited targets by TGFβ1." (PMID 32358507, 2020).
penile squamous cell carcinoma (1 paper, 2025). "Immunohistochemistry (IHC) analysis of eight cytokines (IL-1A, IL-1B, IL-2, IL-6, IL-12, TGF-β1, TNF-α and IFN-γ) was performed in paired tumour tissues and corresponding negative surgical margins from 94 patients with penile squamous cell carcinoma." (PMID 41465261, 2025).
perennial allergic rhinitis (1 paper, 2017). Allergic rhinitis caused by indoor allergens and lasting year round. "The patients with perennial allergic rhinitis and additional high sensitization to SEs demonstrated a higher TNF-α production profile due to macrophage and T cell activation by these toxins." (PMID 29109963, 2017).
peripartum cardiomyopathy (1 paper, 2012). Peripartum cardiomyopathy (PPCM) is an idiopathic, potentially fatal form of dilated cardiomyopathy that develops during the final month of pregnancy or within five months after delivery. "Higher levels of CRP, Fas/Apo-1, TNF alpha and IL-6 have been demonstrated in some population groups with peripartum cardiomyopathy and have implicated a role for inflammatory mediator in the disease process." (PMID 22924131, 2012). "TNF alpha, and other proinflammatory cytokines have been shown to be elevated in a large number of peripartum cardiomyopathy cases and similarly some studies have suggested a role for autoantibodies against normal human cardiac tissues proteins and further research is required in this area." (PMID 22924131, 2012).
Peripheral edema (1 paper, 2018). An abnormal accumulation of interstitial fluid in the soft tissues of the limbs. "Correlation of TNF-α levels with severity of peripheral edema and multigated acquisition (MUGA) technique-derived RVEF." (PMID 29875701, 2018).
peripheral T-cell lymphoma (1 paper, 2024). "Moreover, we identified the downregulation of the TNF signaling pathway, a crucial pathway involved in cell survival, death, and differentiation, as a potential contributor to the development of chemotherapy resistance in peripheral T-cell lymphoma." (PMID 38468267, 2024).
pharyngeal squamous cell carcinoma (1 paper, 2024). A squamous cell carcinoma that arises from the pharynx. "Our study found significantly higher levels of Th1 CKs IL-12p70 and TNF-α in benign lesions compared to patients with pharyngeal squamous cell carcinoma." (PMID 38920620, 2024).
pilonidal cyst (1 paper, 2025). "[99mTc]Tc-anti-TNF-alpha scintigraphy revealed abnormal uptake foci corresponding to both a pilonidal cyst and a clinically inactive lesion." (PMID 40872580, 2025).
placental diseases (1 paper, 2023). "FUT10, involved in the fucosylation of proteins, has been shown to promote the binding of TNF to its receptor, thus promoting the inflammatory reaction, which is relevant for placental diseases." (PMID 36831244, 2023).
Plantar Fascitis (1 paper, 2018). "Plantar Fascitis was noted in 9(17%) ‘other SpA’ and 2(2%) AS patients Seventeen (32%) of ‘other SpA’ patients were on anti-TNF therapy at the last follow-up, whilst four(8%) other patients had previously utilised it." (PMID 29456775, 2018).
pneumonic pasteurellosis (1 paper, 2016). Bovine respiratory disease found in animals that have been shipped or exposed to cattle recently transported. "In addition, the expression of IL1-β and TNF-α were elevated in the respiratory airways and lung lesions of diseased calves with pneumonic pasteurellosis." (PMID 27547520, 2016).
pollen allergies (1 paper, 2012). "In grass pollen allergies, a state of chronic inflammation in the upper airways is reminiscent of allergen-induced activity of the innate immune system, which can be analyzed by the presence of TNF-α and IL-1β on day 1 in allergen-induced in vitro PBMC cultures." (PMID 22315506, 2012).
polycythemia vera (1 paper, 2025). "Our research revealed a link between elevated TNF-α levels and increased mitochondrial mass in platelets from individuals with JAK2 V617F polycythemia vera (PV)." (PMID 40493419, 2025).
postpartum hemorrhage (1 paper, 2021). Hemorrhage defined as a blood loss in excess of 500 mL after vaginal delivery or more than 1000 mL after a cesarean delivery. "TNF-α and IL-8 also significantly correlated with pathological jaundice, postpartum hemorrhage, premature rupture of membranes, HCA, and puerperal infection." (PMID 33765949, 2021).
Premature ovarian insufficiency (1 paper, 2021). Amenorrhea due to loss of ovarian function before the age of 40. "An imbalance between pro-inflammatory cytokines such as IFNγ and TNFα and anti-inflammatory cytokines such as IL-10 has also been reported to play a critical role in the pathological mechanism of premature ovarian insufficiency." (PMID 34868029, 2021).
Primary hypothyroidism (1 paper, 2021). A type of hypothyroidism that results from a defect in the thyroid gland. "TNF-α which is raised in primary hypothyroidism can lead to localized DHEA deficiency in synovial cells." (PMID 33592022, 2021).
primary progressive-MS (1 paper, 2013). "In controls, there were positive correlations between circulating leptin and resistin with TNF-α and IL-1β in subgroup analysis, the highest levels of TNF-α, IL-1β, hs-CRP, resistin and leptin were observed in primary progressive-MS (PP-MS) patients." (PMID 24098530, 2013).
Psoas abscess (1 paper, 2024). Abscess of the PSOAS MUSCLES resulting usually from disease of the lumbar vertebrae, with the pus descending into the muscle sheath. "Psoas abscess persisted despite anti-TNFα treatment in 1 patient." (PMID 38957691, 2024).
Psychotic episodes (1 paper, 2022). Periods of time during which an individual experiences significant disturbances in their thoughts, perceptions, emotions, and behavior, resulting in a loss of touch with reality. "It is possible that PSD symptoms may have been provoked by psychological stress; however, the presence of elevated TNF-α may be associated with both primary and secondary psychotic episodes." (PMID 35409462, 2022).
radiation-induced brain injury (1 paper, 2017). An injury to the brain which results results from exposure to radiation. "Patients with radiation-induced brain injury show high levels of extracellular ATP, IL-6, and TNF in cephalorachidian fluid." (PMID 28962574, 2017).
RASopathy (1 paper, 2019). Developmental syndromes caused by germline mutations (or in rare cases by somatic mosaicism) in genes that alter the Ras subfamily and mitogen-activated protein kinases that control signal transduction. "The astrocyte-secreted molecule, TNFα, is a major contributor to learning and memory, and astrocyte-mediated perineuronal net formation around PV+ GABAergic neurons is thought to contribute to RASopathy phenotypes." (PMID 31017896, 2019).
Rectal prolapse (1 paper, 2019). Protrusion of the rectal mucous membrane through the anus. "After LPS treatment, secreted protein levels of both TNFα and IFN-γ were significantly higher in BMDM conditioned media obtained from cells derived from Gab2/3−/− mice with rectal prolapse compared with WT." (PMID 30936879, 2019).
relapsing fever (1 paper, 2019). Relapsing fever is an infection caused by bacteria of the genus Borrelia, excluding those responsible for Lyme disease belonging to the Borrelia burgdorferi complex. "A small controlled trial of 40 relapsing fever patients was conducted in which one half of the patient group received antibody fragments specific to TNF-alpha in order to prevent TNF-alpha activity." (PMID 31888245, 2019). "For relapsing fever, a tick-borne illness caused by the spirochete Borrelia recurrentis, the JHR symptoms that occur after penicillin treatment are preceded by an increase in blood serum levels of cytokine TNF-alpha and followed by increases in IL-6 then IL-8." (PMID 31888245, 2019).
Renal artery stenosis (1 paper, 2023). The presence of stenosis of the renal artery. "TAK patients with CAL had significantly higher CRP,WBC, PLT,TNF-α and IL-2R levels (P < 0.05), lower HGB (P = 0.01), lower rate of renal artery stenosis (RAS) (P = 0.009)." (PMID 37118779, 2023).
retinal artery occlusion (1 paper, 2010). An occlusion of the retinal artery. "Similar results have been seen in a mouse model of central retinal artery occlusion, where TNF-α mRNA levels were increased early but then almost reached control levels again after 7 days." (PMID 21152396, 2010).
retroperitoneal fibrosis (1 paper, 2021). "Interestingly, no TNF-alpha was identified in patients’ aortas, suggesting that TNF-alpha is not a significant factor in retroperitoneal fibrosis development." (PMID 33808093, 2021).
salivary carcinoma (1 paper, 2020). "However, the individual ceramide unit of GlcCer activates apoptosis in salivary carcinoma cells as well as tumor necrosis factor-α (TNFα)-stimulated cultured lung endothelial cells." (PMID 32961778, 2020).
salivary gland stones (1 paper, 2021). "Our finding that TNFα had a MUC8-like distribution in the studied salivary gland stones strongly supports this inflammatory hypothesis of increased MUC8 content in salivary stones." (PMID 34943565, 2021).
Salmonella gastroenteritis (1 paper, 2016). Poisoning caused by ingestion of food harboring species of salmonella. "There was a significant increase in TNF-α and IL-17 in cecal supernatants from AIEC-colonized mice exposed to Salmonella gastroenteritis compared to either monocolonized mice or uninfected controls." (PMID 27711220, 2016).
selenium deficiency (1 paper, 2024). A nutritional deficiency disease resulting from inadequate selenium levels in the body, which can lead to impaired function of selenoproteins essential for antioxidant defense and thyroid hormone metabolism. "Selenium deficiency in the body increases T cell activity, disrupts the balance between Th1 and Th2, leads to excessive cytokine production such as tumor necrosis factor-alpha (TNF-α), and reduces the number of regulatory T cells." (PMID 38999993, 2024).
sensory impairment (1 paper, 2020). "Secondly, more importantly, the expression of GFAP and inflammatory cytokines IL‐1β, IL‐6, and TNF‐α were increased both in PD patients with and without sensory impairment." (PMID 31828965, 2020).
Sinus bradycardia (1 paper, 2022). Bradycardia related to a mean resting sinus rate of less than 50 beats per minute. "The results of the network screening of core targets showed that AKT1, IL6, VEGFA, and TNF were the top 4 core target proteins in terms of degree value, and maybe the most core targets for the treatment of sinus bradycardia with Yohimbe." (PMID 36626429, 2022). "There are 54 targets of action in the treatment of sinus bradycardia, of which 19 targets such as AKT1, IL6, TNF, and VEGFA are the core targets of Datura metel in the treatment of sinus bradycardia." (PMID 36626429, 2022).
skin nodules (1 paper, 2025). "Another study reported an increase in TNF-α levels in buffalo infected with LSDV, 21 days after the appearance of skin nodules." (PMID 41459038, 2025).
skin pigmentation disorder (1 paper, 2025). A pigmentation disease that involves the zone of skin. "In essence, TLNVs mitigate the expression of pro-inflammatory cytokines TNF-α and IL-1β, ameliorate the inflammatory milieu, and foster melanin degradation through an autophagy pathway governed by LC3B and P62, underscoring its prospective utility in ameliorating skin pigmentation disorders." (PMID 40735705, 2025).
sphenoidal sinusitis (1 paper, 2009). "Only 5/20 patients were treated with TNFα antagonists (invasive lung aspergillosis, n = 3; intracranial aspergillosis, n = 1; and sphenoidal sinusitis, n = 1)." (PMID 19886992, 2009).
spinal cord tumors (1 paper, 2023). "In rat spinal cord tumors, TNF-a is able to enhance glutamate-mediated neuronal cell deaths, while TNF antagonists are able to reduce inflammatory responses and tissue damage." (PMID 38022526, 2023).
spinal epidural abscess (1 paper, 2026). "While spinal epidural abscess (SEA) is a well-recognized neurosurgical emergency, its diagnosis remains a formidable challenge when presenting with atypical symptoms such as dysphagia, particularly in patients under anti-tumor necrosis factor (TNF) therapy." (PMID 42220849, 2026).
spindle cell carcinomas (1 paper, 2022). "When injected via tail vein, KALLU+ lung SCC cells that highly expressed TNFR1/TNF, Sox2, c-Myc, Twist1, Bcl2, and UBCH10, generated dedifferentiated spindle cell carcinomas with epithelial–mesenchymal transition markers in mouse lungs." (PMID 36270982, 2022).
spleen infarcts (1 paper, 2022). "For APS, spleen infarcts could be the cause; for IBD, TNF seems to play a role, and SLE inflammation could be the key." (PMID 36148466, 2022).
spongiotic dermatitis (1 paper, 2021). A generic term for a broadly defined histopathologic pattern characterised by “eczema”, often associated with an increase in eosinophils occurring in a background of contact dermatitis, atopy and drug reactions. "In addition, up to 35% of psoriasiform biopsies in anti-TNF-α treated patients show a spongiotic dermatitis." (PMID 33802483, 2021).
spotted fever (1 paper, 2018). A type of tick-borne disease which presents on the skin caused by bacteria of the genus Rickettsia. "Increased IFN-γ and TNF-α levels, as reported in patients with Japanese spotted fever, ATBF and MSF, were not detectable in R. felis infected patients." (PMID 29736763, 2018).
staphylococcal pneumonia (1 paper, 2024). Pneumonia caused by infections with bacteria of the genus staphylococcus, usually with staphylococcus aureus. "Overwhelming inflammation, such as induction of TNF-α responses, has been reported to exert a negative effect on the lung tissue during staphylococcal pneumonia." (PMID 37982695, 2024).
Stress urinary incontinence (1 paper, 2024). Involuntary urine leakage synchronous with exertion, or actions such as sneezing, or coughing. "Another study similarly noted that TNF-α and MIP-1β had an AUROC greater than 0.70 in predicting IC/BPS, including both Hunner-type IC/BPS and NHIC, compared with women with stress urinary incontinence." (PMID 39273307, 2024).